VWF (von Willebrand factor)
Diseases named in the same sentence as VWF in open-access papers (continued):
Sharing a sentence is not in itself a finding about the gene and the disease.
Hepatitis (4 papers, 2020 to 2024). Inflammation of the liver. "We confirmed that liver inflammation and fibrosis, as assessed by non-invasively FIB-4 and LSM, were independently associated with a procoagulant shift, as a consequence of upregulation of vWF, circulating F8, and reduction of PC, resulting in increased activation of coagulation and fibrinolysis." (PMID 36313186, 2022).
Hypercortisolism (4 papers, 2023 to 2025). "Hypercortisolism may also affect the multimeric structure of vWF causing an overexpression of abnormally high molecular weight multimers, capable of inducing spontaneous platelet aggregation." (PMID 38836224, 2024). "Hypercortisolism, in turn, is known to enhance haemostatic factors, specifically vWF, PAI-1, and FVIII levels while decreasing fibrinolysis activity." (PMID 37887417, 2023).
invasive breast carcinoma (4 papers, 1995 to 2023). A carcinoma that infiltrates the breast parenchyma. "There is a positive correlation between VWF concentration and invasive breast carcinoma, with higher VWF to serum soluble E-selectin ratios being associated with poorly differentiated tumors." (PMID 35327035, 2022).
invasive ductal carcinoma (4 papers, 2005 to 2021). "Notably, similar research in female invasive ductal carcinoma of the breast using VWF MVD assessment techniques also demonstrated correlation between central, peripheral and highest microvessel densities." (PMID 15743520, 2005).
liver failure (4 papers, 2022 to 2023). A liver disease characterized by the liver losing or has lost all of its function. "Our group further evaluated changes in ADAMTS-13/VWF in patients with advanced chronic liver disease in relation to markers of endotoxemia such as LPS, confirming the strong association between decreased ADAMTS-13/VWF, chronic low-grade inflammation, and risk of liver failure." (PMID 37443746, 2023). "In patients with hepatic insufficiency, high levels of von Willebrand factor and underexpressed low-density lipoprotein receptor-associated protein together maintain high plasma levels of factor VIII." (PMID 37875995, 2023). "Recent studies have begun to focus on the role of VWF in liver failure." (PMID 36359765, 2022). "However, the source of VWF during liver failure remains unclear." (PMID 36359765, 2022).
lymph node metastasis (4 papers, 2015 to 2019). "High microvessel counts, as determined by von Willebrand factor (vWF) staining, are associated with high levels of RAGE, LMP1, and lymph node metastasis, suggesting a role for RAGE in EBV-induced angiogenesis." (PMID 31354653, 2019). "Although lymphatic ECs contain WPBs and store VWF, the roles of VWF in the lymphatics and in lymph node metastasis are unknown." (PMID 27602496, 2016).
mental disorder (4 papers, 2013 to 2021). A disease that has its basis in the disruption of mental process. "In addition, cohort members who had a parent with a mental illness also had higher vWF levels in mid-life which remained upon adjustment (3.42, 95% CI: 0.19, 6.74)." (PMID 32201253, 2020).
monoclonal gammopathies (4 papers, 2014 to 2024). "Among the mechanisms proposed for AVWD in monoclonal gammopathies include von Willebrand factor (VWF) specific antibodies and the VWF multimers being absorbed onto the lymphoplasmacytic cells." (PMID 35756635, 2022). "The VWF:pp/VWF:Ag ratio is only increased in 55% of monoclonal gammopathies inducing type 1 AVWS." (PMID 39228434, 2024).
multiple sclerosis (4 papers, 2016 to 2023). A progressive autoimmune disorder affecting the central nervous system resulting in demyelination. "The connection between the biology of multiple sclerosis and vWF, which was decreased in the CSF of CDMS patients compared to non-MS, is less opaque; vWF and/or Weibel-Palade bodies negatively regulate BBB permeability changes in MS-like lesions." (PMID 35185866, 2021). "To investigate the association of VWF gene to human HSE disease, we genotyped 27 SNPs within the VWF gene and one SNP within the TNFRSF1A adjacent gene located on chromosome 12 using Taqman in 115 HSE cases and 158 EIMS (epidemiological investigation of multiple sclerosis project) controls." (PMID 27224245, 2016).
osteonecrosis (4 papers, 2016 to 2024). A none disease characterized by death of bone tissue due to a lack of blood supply. "Studies on biomarkers related to VWF and osteonecrosis of the femoral head have reported upregulation of VWF expression in patients with osteonecrosis." (PMID 38825675, 2024). "The first study reporting an association between vWF and osteonecrosis included 68 patients with non-traumatic ONFH and 36 healthy controls." (PMID 35054824, 2022). "Although not reported in patients with ONJ, high FVIII and vWF levels are currently recognized as contributors to osteonecrosis." (PMID 35054824, 2022).
parasitemia (4 papers, 2015 to 2025). "In contrast only peripheral parasitemia was associated with endothelial activation and the Weibel Palade Body products Ang-2 and VWF." (PMID 25569250, 2015). "In contrast to the limited changes in platelet reactivity and coagulation, plasma concentrations of total and active VWF were markedly increased at the moment of asexual parasitemia, which is in line with previous reports." (PMID 35839244, 2022).
platelet disorders (4 papers, 2006 to 2022). "The influence of common variables influencing PFA-100 results such as acquired or congenital platelet disorders and VWF levels has been accurately excluded in our study populations." (PMID 16916446, 2006). "We considered using ddAVP, not to correct a VWF defect, but to improve hemostasis in qualitative platelet disorders (which are in her differential diagnosis)." (PMID 30581553, 2018). "Additionally, the thrombosis, inflammation, and platelet disorders may affect the ADAMTS13:AC, VWF:Ag, and Et levels in patients with LC." (PMID 35407443, 2022).
rheumatoid arthritis (4 papers, 2013 to 2025). A chronic, systemic autoimmune disorder characterized by inflammation in the synovial membranes and articular surfaces. "Elevated vWF and VCAM-1 concentrations as markers of endothelial activation were found together with higher skin autofluorescence in patients with rheumatoid arthritis." (PMID 23671885, 2013).
sarcoma (4 papers, 2014 to 2025). A usually aggressive malignant neoplasm of the soft tissue or bone. "Undetermined tumours should be subjected to further immunohistochemistry, such as analysis of smooth-muscle actin, desmin, vimentin, von Willebrand factor or neuron-specific enolase, before a final diagnosis of “poorly differentiated sarcoma” should be made." (PMID 25563490, 2015). "Increased RAB27A, SYTL2, and VWF expression was observed in human ASPS among the six sarcoma types." (PMID 37029109, 2023). "As they can be of a very heterogeneous origin, there are no specific immunohistopathological markers of intimal sarcomas but a panel including endothelial differentiation markers CD31, CD34, and von Willebrand factor may increase sensitivity." (PMID 40034398, 2025).
systemic sclerosis (4 papers, 2019 to 2023). A chronic disorder, possibly autoimmune, marked by excessive production of collagen which results in hardening and thickening of body tissues. "The 4 ± 1% of pulmonary arterioles in systemic sclerosis (SSc)-PAH patients showed vWF/SMAα co-localization." (PMID 33371458, 2020).
thyrotoxicosis (4 papers, 2010 to 2025). A hypermetabolic syndrome caused by the elevation of thyroid hormone levels in the serum. "Thyrotoxicosis should be considered as a minor (yet important) transient risk factor for thrombosis, as high levels of fT4 combine with other stimuli to cross the so-called “thrombotic threshold”, mainly by increasing FVIII and vWF." (PMID 39518686, 2024). "Thyrotoxicosis increases plasma levels of tissue factor, Factor VIII, Factor IX, von Willebrand Factor, fibrinogen, D-dimer, and plasminogen activator inhibitor-1, these factors are all related to the formation of CVST." (PMID 35794521, 2022).
type 1 diabetes (4 papers, 2015 to 2026). "Elevated plasma vWF levels have been observed in type 1 diabetes (T1D) and are significantly higher in DN patients compared to those without kidney disease, suggesting its role in the early diagnosis of DN." (PMID 39872596, 2024). "We have investigated whether von Willebrand factor, ADAMTS13 (a disintegrin and metalloproteinase with thrombospondin type 1 motif, member 13), and D-Dimer were associated with different levels of renal function in patients with type 1 diabetes." (PMID 26168189, 2015).
vascular dementia (4 papers, 2010 to 2025). A degenerative vascular disorder affecting the brain. "For example, two meta-analyses suggested potential relationships between higher blood VWF levels and an increased risk of vascular dementia, although results from individual investigations are conflicting." (PMID 40969184, 2025). "In patients with acute ischemic stroke and vascular dementia, vWF levels have also been shown to be increased." (PMID 20509943, 2010). "Angiogenic signaling factors are increased in brains of people with AD and vascular dementia, and multiple serum biomarkers of vascular functions including angiogenesis (vascular endothelial growth factor; von Willebrand factor) are elevated after experimental TBI." (PMID 35012589, 2022).
vascular occlusion (4 papers, 2011 to 2022). "The Hb-bound VWF multimers are elevated parallely with the level of ECHb in patients' plasma, and is associated with the pathogenesis of thrombosis and vascular occlusion in SCA." (PMID 21490767, 2011). "Due to the excessive secretion of the von Willebrand factor (vWF) by damaged endothelial cells, the coagulation cascade is over-activated, resulting in vascular occlusion." (PMID 36132154, 2022). "Our data provide strong evidence that in addition to the VWF-mediated bacterial attachment to the vascular endothelium, this interaction induces the formation of bacterial aggregates leading to distributed vascular occlusions." (PMID 30972039, 2019).
von Willebrand disease type 2B (4 papers, 2015 to 2023). "Gain of function mutations in VWF, as seen in von Willebrand disease type 2B were shown to impair activation of the αIIbβ3 integrin." (PMID 30849118, 2019). "In patients with von Willebrand disease type 2B (VWD type 2B), a disease characterized by gain-of-function mutations in VWF that enhance its spontaneous binding to the platelet GPIbα, increased platelet-VWF binding is associated with thrombocytopathy due to inhibition of αIIbβ3 activation." (PMID 28934202, 2017).
acute lymphoblastic leukaemia (3 papers, 2016 to 2022). "VWF levels are significantly increased compared to healthy controls in a variety of both hematological and non-hematological solid-organ malignancies, including breast, colorectal, non-small cell lung cancer, gastric, prostate, and acute lymphoblastic leukemia." (PMID 35327035, 2022).
acute myeloid leukemia (3 papers, 2012 to 2022). Acute myeloid leukemia (AML) is a group of neoplasms arising from precursor cells committed to the myeloid cell-line differentiation. "The expression of serum MMP-2 and von Willebrand factor (vWF) in patients with acute myeloid leukemia (AML) at different risks and their predictive value and prognostic impact were investigated." (PMID 35935313, 2022).
antithrombin deficiency (3 papers, 2017 to 2024). "Chemotherapeutic agents are also highly thrombogenic, including asparaginase, which causes antithrombin deficiency and steroids which increase factor VIII/von Willebrand factor complex." (PMID 28168186, 2017).
Anxiety (3 papers, 2018 to 2023). Intense feelings of nervousness, tension, or panic often arise in response to interpersonal stresses. "Anxiety/stess related increases in VWF is particularly relevant in pediatric patients." (PMID 37601016, 2023).
arterial diseases (3 papers, 2016 to 2025). "We think VWF and OPG are markers of endothelial perturbation or damage as a result of arterial disease." (PMID 27387019, 2016).
arthropathy (3 papers, 2022). Any disorder of the joints. "While the influence other factors like age (p = 0.884), the numbers of arthropathy (p = 0.145), vWF:Ag level (p = 0.275), FVIII trough level of prophylaxis (p = 0.085) and the degree of arthropathy (p = 0.314) showed no statistical significance." (PMID 36389359, 2022).
Ascites (3 papers, 2022 to 2026). Accumulation of fluid in the peritoneal cavity (between the layers of the peritoneum that lines the abdomen). "In fact, ADAMTS-13/VWF was significantly lower in patients who developed complications (ascites, variceal hemorrhage, and hepatocellular carcinoma) than in those who did not, while LPS showed an opposite trend." (PMID 37443746, 2023). "Specifically, VWF levels above 213% were predictive of new-onset ascites, whereas levels above 466% or FVIII/PC above 3.29% predicted variceal bleeding during follow-up." (PMID 37443746, 2023). "Previous work has shown that a decrease in ADAMTS13:AC and increase in VWF:Ag levels are associated with hepatic encephalopathy, HRS, and ascites." (PMID 35407443, 2022). "In addition, levels of VWF, FVIII, and FVIII/PC were independently associated with the development of ascites and variceal bleeding." (PMID 37443746, 2023). "We speculate that the development of hepatic encephalopathy, HRS, and ascites is associated with platelet microthrombi formation through an imbalance between ADAMTS13 enzyme and VWF substrate." (PMID 35407443, 2022).
blood disease (3 papers, 2014 to 2025). A disease that occurs in the blood. "Our findings are also relevant for VWF-pertinent blood diseases resulting from various VWF mutations." (PMID 29079767, 2017). "Considering vWF:Ag levels are affected by a number of factors, the present study excluded patients with infections and blood diseases." (PMID 24926346, 2014).
chronic heart failure (3 papers, 2015 to 2023). "Since many chronic heart failure patients are routinely prescribed either low dose aspirin or anticoagulants, whether these regimens may be masking progressive reductions in vWF secretion (and hence thrombus formation propensity) is an unknown that may require future investigations." (PMID 26565707, 2015). "Patients with chronic heart failure that have been treated with ACE inhibitors had reduced fibrinogen and endothelial von Willebrand factor levels when compared with baseline." (PMID 29545754, 2018).
colon adenocarcinoma (3 papers, 2017 to 2025). "Moreover, high mutation rates inFVIII,VWF, andADAMTS13were also found in patients with diffuse large B cell lymphoma (22.9%), lung small cell carcinoma (20.7%), and colon adenocarcinoma (19.4%)." (PMID 29152610, 2017). "Additionally, OX40 was positively correlated with the expression of the canonical EC marker genes CD31, VWF, and CD34 in The Cancer Genome Atlas Colon Adenocarcinoma (TCGA-COAD) dataset." (PMID 40026246, 2025).
coronary thrombosis (3 papers, 2010 to 2020). Coagulation of blood in any of the coronary vessels. "Concentration of plasma ADAMTS13 decreases when vWF level increases during acute formation process of coronary thrombosis." (PMID 32293292, 2020).
diabetic retinopathy (3 papers, 2017 to 2026). "Further to assess the therapeutic efficacy of diabetic retinopathy, we showed Chit-DC-VB12-Scu down-regulated central retinal artery resistivity index and the expression of angiogenesis proteins (VEGF, VEGFR2, and vWF) of retinas in type II diabetic rats." (PMID 28249594, 2017).
emphysema (3 papers, 2010 to 2023). "Moreover, increased vWF levels was observed on exposure to PHMG on-chip which is in line with current research findings confirming that elevated vWF amount is associated with inflammation and emphysema pathogenesis." (PMID 36959848, 2023).
epilepsy (3 papers, 2020). A brain disorder characterized by episodes of abnormally increased neuronal discharge resulting in transient episodes of sensory or motor neurological dysfunction, or psychic dysfunction. "CACNA2D2 is an important epilepsy-related calcium channel protein involved in small molecule ligand interactions as well as neuronal cell death pathways VWF is involved in inflammation, seizures, neurodegeneration, and blood brain barrier permeability." (PMID 32823271, 2020).
fibroids (3 papers, 2021 to 2022). "Using antibodies of the von Willebrand factor (vWF) as a vessel marker for angiogenesis, a significantly decreased angiogenic response in GnRHa-treated fibroids was noted." (PMID 34442017, 2021). "A total of eight leiomyoma-related DEGs (EGR1, CEBPB, IL6, PECAM1, VWF, TNFRSF1A, CD34 and ACE) were found upregulated in MF versus M only." (PMID 33807176, 2021). "VWF, an endothelial and tumor progression marker, was upregulated in MyoF samples compared with myometrium from women without fibroids, but it was not differentially expressed in the F tissues." (PMID 36066972, 2022).
Gastrointestinal angiodysplasia (3 papers, 2014 to 2025). Dysplasia affecting the vasculature of the gastrointestinal tract. "Being the latters the most hemostatically competent form of von Willebrand factor, this favors a vicious circle that aggravates the bleeding from GI angiodysplasia and the consequent IDA." (PMID 24795637, 2014). "Any cardiovascular disease that accelerates VWF clearance may lead to bleeding from coexisting gastrointestinal angiodysplasia." (PMID 36449459, 2022).
hemarthrosis (3 papers, 2014 to 2021). Bleeding into the joints. "The FVIII.VWF complex may act as an anti-resorption factor both in normal physiology and following hemarthrosis." (PMID 31594977, 2019). "In conclusion, mice with complete FIX or FVIII deficiency (but not VWF deficiency) display similarly defective congenital bone homeostasis and bone remodeling following hemarthrosis." (PMID 31594977, 2019). "Patient ID 4 was born of consanguineous marriage with history of increased bleeding tendency, ecchymosis, gum bleed and hemarthrosis with FVIII:C and VWF:Ag levels of <1 IU/dL." (PMID 24675615, 2014). "Unilateral induced hemarthrosis causes further bone damage in both FVIII−/− and FIX−/− mice, but has little effect on VWF−/− bone health, indicating that the FVIII.VWF complex is not required for normal bone remodeling in vivo." (PMID 31594977, 2019).
kidney injury (3 papers, 2016 to 2019). Trauma to the kidney. "We also detected elevated levels of anti-ADAMTS13 and anti-vWF antibodies in MHTN related kidney injury." (PMID 27278520, 2016).
leptospirosis (3 papers, 2017 to 2019). A contagious bacterial infection caused by spirochetes of the genus Leptospira. "High plasma VWF levels, together with elevations in other endothelial cell activation markers, were recently reported in patients with leptospirosis." (PMID 28934202, 2017). "Third, circulating platelets in probable leptospirosis patients bind more VWF and this has a strong negative association with platelet number, in contrast with the plasma coagulation marker TAT complexes." (PMID 28934202, 2017). "Platelets of leptospirosis patients also demonstrated increased binding with von Willebrand factor (VWF), and a strong negative correlation with platelet count suggesting that this binding is important for platelet clearance." (PMID 28934202, 2017).
leukocytosis (3 papers, 2013 to 2023). "Laboratory investigation on presentation revealed leukocytosis (WBC 21 K/microliter), markedly elevated inflammatory markers (C-reactive protein (CRP) (23 mg/dl), erythrocyte sedimentation rate (ESR) (79 mm/h), fibrinogen (840 mg/dl), von Willebrand factor 289% (normal 60-160%), and hypoalbuminemia." (PMID 35012585, 2022).
liver cancer (3 papers, 2022 to 2023). An epithelial or non-epithelial malignant neoplasm that arises from the liver. "VWF has also been mentioned several times as a biomarker to predict the prognosis of liver cancer." (PMID 35639708, 2022).